CXCR4 (C-X-C motif chemokine receptor 4)
Diseases named in the same sentence as CXCR4 in open-access papers (continued):
Sharing a sentence is not in itself a finding about the gene and the disease.
gastric cancer (continued). "Our investigation reveals that the protein level of CXCR4 was upregulation in gastric cancer tissues compared with the paired non-tumoral tissues, and its correlation with poor prognosis of patients with gastric cancer was evaluated." (PMID 23936528, 2013). "Immunohistochemical staining of CXCR4 levels was statistically analyzed to determine their relationship with various clinicopathologic features of overall 97 gastric cancer patients." (PMID 23936528, 2013). "In our study, we demonstrated that the overall survival of gastric cancer patients presented high intratumoral CXCR4 expression with TNM stage iii+iv was significantly poorer than those patients with low CXCR4 intratumoral expression (P<0.001)." (PMID 23936528, 2013). "CXCR4 immunoreactivity was mainly in the membranes and cytoplasm of gastric cancer cells and the intensity of the immunohistochemical staining was variable." (PMID 23936528, 2013). "The protein level of CXCR4 was upregulation in gastric cancer tissues and upregulated expression of CXCR4 was only significantly associated with Lauren classification (P<0.001)." (PMID 23936528, 2013). "And the profound molecular roles of CXCR4 in gastric cancer progression remain far from being fully elucidated and await further investigation." (PMID 23936528, 2013). "In summary, our results demonstrate that increased intratumoral CXCR4 expression predicts independently poor postoperative overall survival of patients with gastric cancer." (PMID 23936528, 2013). "To further investigate the prognostic value of CXCR4 expression in gastric cancer patients, we compared cancer-specific survival according to intratumoral CXCR4 expression, and Kaplan-Meier survival analysis was performed." (PMID 23936528, 2013). "These close connections between RhoE and CXCR4 strongly suggested that RhoE enhanced metastasis by up-regulating CXCR4 in gastric cancer." (PMID 24312338, 2013). "Increased CXCR4 expression in gastric cancer tissues was positively correlated with poor overall survival of gastric cancer patients (P<0.001)." (PMID 23936528, 2013). "Relation between intratumoral CXCR4 expression and clinical characteristics in patients with gastric cancer." (PMID 23936528, 2013). "In the present study, we seek to determine the clinical and prognostic implications of CXCR4 expression in gastric cancer." (PMID 23936528, 2013). "Previous study had been reported that CXCR4 was a potential marker for docetaxel chemosensitivity in gastric cancer." (PMID 23936528, 2013). "Applying the prognostic value of intratumoral CXCR4 density to TNM stage system showed a better prognostic value in patients with gastric cancer." (PMID 23936528, 2013). "In conclusion, intratumoral CXCR4 expression was recognized as an independent prognostic marker for the overall survival of patients with gastric cancer." (PMID 23936528, 2013). "CXCR4 is assumed to be involved in metastasis of non-small-cell lung, breast, pancreatic, prostate, gastric cancer, and peritoneal carcinomatosis." (PMID 23231927, 2012). "Others findings have revealed TNF-α antagonists can inhibit the upregulation of CXCR4 expression by H. pylori, and both it and CXCR4 antagonists can suppress the increased migration of gastric cancer cells in vitro." (PMID 20699000, 2010). "CXCR4 mRNA was determined by real-time reverse-transcription PCR in 34 gastric cancers, and its expression in each specimen was standardized to GAPDH expression." (PMID 20699000, 2010). "First, there was a significant upregulation of CXCR4 in gastric cancer cells after they were treated with exogenous TNF-α." (PMID 20699000, 2010). "Overexpression of CXCR4, whose involvement in various human tumors is well known, was frequently observed in gastric cancer tissues to increase gastric cancer metastasis." (PMID 20699000, 2010). "The overall findings led to our conclusion that TNF-α, with itself involved in the metastasis of gastric cancer, upregulates CXCR4 expression." (PMID 20699000, 2010).
gastric cancer (continued). "Another focus of our attention is shed on CXCR4, the most common chemokine receptor overexpressed in a series of cancers (gastric cancer included) by far." (PMID 20699000, 2010). "Spearman's rank correlation test further verified a positive correlation of CXCR4 expression with TNF-α in these 34 gastric cancers (P < 0.01)." (PMID 20699000, 2010). "Next, the CXCR4 expression within a co-culture system was examined, since tumor-associated macrophages also serve as a source of TNF-α in the gastric cancer microenvironment." (PMID 20699000, 2010). "It appears not to be a coincidence that there is also an overexpression of CXCR4 and an obvious involvement in gastric cancer metastasis." (PMID 20699000, 2010). "Our findings demonstrated that H. pylori upregulates CXCR4 expression in gastric cancer through TNF-α." (PMID 20699000, 2010). "The candidate genes CXCL12 and its receptor CXCR4 were validated by real-time reverse-transcription polymerase chain reaction in an independent set of 37 gastric carcinomas." (PMID 20386750, 2010). "The differential expression of CXCL12- and CXCR4-mRNA was validated by real-time RT-PCR in an independent set of 37 intestinal type gastric carcinoma samples." (PMID 20386750, 2010). "There is some evidence that CXCR4 expressing gastric carcinomas more likely develop a peritoneal spread of the tumour, and malignant ascites contains high concentrations of CXCL12." (PMID 20386750, 2010). "About one third of the examined gastric carcinomas showed CXCR4 positive tumour- surrounding microvessels." (PMID 20386750, 2010). "An overall of 83% (243 of 293) of the gastric carcinomas were immunonegative for CXCR4, most of them showing concomitant CXCR4 positive leucocytes as an internal positive control." (PMID 20386750, 2010). "CXCR4 related signaling has been proposed as the promising therapeutic target of gastric cancer." (PMID 38221932, 2024). "MMP9 and CXCR4 were upregulated in gastric cancer in copy number analysis." (PMID 38457601, 2024). "All these revealed the significant role of CXCR4 in gastric cancer." (PMID 38221932, 2024). "Additionally, it has been reported that the heightened expression of PGK1, along with its signaling targets, CXCR4 and β-catenin, in gastric cancer cells promotes peritoneal carcinomatosis." (PMID 38136210, 2023). "The results of clone formation and transwell assays showed that the addition of the CXCL12/CXCR4 signaling pathway by the inhibitor, AMD3100, reverses the increase in the proliferation and migration of gastric cancer cells that was caused by KDM6B ectopic expression." (PMID 36564369, 2022). "In addition, CD44, Wnt2, Bmi1, Notch1, Oct4, Sox2, Nanog, C-mys, ABCG2, CXCR4 and other “stemness associated genes” are highly expressed in the CD44+ gastric cancer cell population." (PMID 36316684, 2022). "Our data confirmed the key role of the SDF-1/CXCR4 axis in the motility of gastric cancer cells." (PMID 35328253, 2022). "In this study, we found that curcumol could reduce the SDF-1α/CXCR4/NF-κB protein expression in gastric cancer cells." (PMID 36159583, 2022). "CXCL12/CXCR4 signaling-mediated macrophage polarization can trigger gastric cancer metastases." (PMID 35795038, 2022). "Several studies have demonstrated PGK1 can enhance the proliferation and migration ability of tumors by activating CXCR4 in gastric cancer and neuroblastoma, but PGK1/CXCR4/ERK molecules and related signaling pathways have not been investigated in RCC in previous reports." (PMID 35121728, 2022). "However, other studies suggested that the upregulated expression of CXCR4 is an independent prognostic factor for overall survival following gastrectomy of patients with gastric cancer." (PMID 35877436, 2022). "Multiple studies indicated that CXCR4 could promote the metastasis, invasion, and migration of gastric cancer." (PMID 33522355, 2021). "We have verified the expression of CXCR4 in gastric cancer cells." (PMID 34759953, 2021).
gastric cancer (continued). "CXCL12 induces migration via Src-mediated CXCR4-EGFR cross-talk in gastric cancer cells." (PMID 32903764, 2020). "CXCR4 was related to altered immune cells, which can affect the prognosis of gastric cancer." (PMID 32983229, 2020). "CXCR4 positivity of primary gastric carcinoma also significantly correlated with the development of PM, suggesting that the CXCR4/CXCL12 axis might play an important role in the development of PM from gastric carcinoma." (PMID 31198853, 2019). "CXCR4 expression is closely associated with lymph node metastasis, the clinical stage, and the histological grade in CRC and other gastrointestinal cancers such as gastric cancer." (PMID 29887884, 2018). "Finally, we confirmed that B7-H3 and CXCR4 colocalize in gastric cancer cells and can interact directly." (PMID 29069741, 2017). "To determine how regorafenib affected proliferation and invasion in gastric cancer cells, we then investigated whether regorafenib modulated the expression of CXCR4 in gastric cancer." (PMID 28489887, 2017). "The anti-tumor effects of regorafenib related to the decreased expression of CXCR4, and elevated expression and activation of CXCR4 could reverse the inhibition effect of regorafenib on gastric cancer cells." (PMID 28489887, 2017). "Our findings revealed that CXCR4 might mediate the anti-tumor effect of gastric cancer to regorafenib, and might be a novel biomarker for patients selecting of regorafenib." (PMID 28489887, 2017). "We then determined whether regorafenib inhibited and CXCR4 enhanced the Wnt/β-catenin signaling pathway in gastric cancer." (PMID 28489887, 2017). "In addition, it is reported that blocking the CXCR4/mTOR signalling pathway induces the anti-metastatic properties and autophagic cell death in peritoneal disseminated gastric cancer cells." (PMID 27517626, 2016). "Fibrocytes derived from bone marrow may migrate into the microenvironment of gastric cancer by SDF-1/CXCR4 system, and enhance the tumor proliferation and fibrosis as CAFs." (PMID 24792410, 2015). "We have to consider, however, that our study involved a limited number of patients (43 patients), and more studies with a larger number of gastric cancer patients are required to determine correlation of nuclear or cytoplasmic CXCR4 expression with survival of gastric patients." (PMID 24659999, 2014). "However, extensive research is still required to clarify the biological function of nuclear CXCR4 in gastric cancers." (PMID 24659999, 2014). "In addition, it was revealed that the gene and protein expression levels of Gli1 and CXCR4 were consistently downregulated in the gastric cancer cells when high concentrations of cyclopamine were applied." (PMID 24765141, 2014). "PGK1 also appears to be a crucial enzyme for peritoneal dissemination of gastric cancer in both CXCR4/SDF1-dependent and by CXCR4/SDF1-independent mechanisms, making high levels of PGK1 essential for tumor growth and metastasis and showing a direct relationship between PGK1 signalling and CXCR4." (PMID 24376734, 2013). "RhoE might thus function as an effector of invasion and metastasis in gastric cancer by augmenting the expression of CXCR4." (PMID 24312338, 2013). "Further investigation showed that up-regulation of CXCR4 in gastric cancer cells could partially restore the invasive ability, which was suppressed by RhoE knock-out." (PMID 24312338, 2013). "Aberrant chemokine (C-X-C motif) receptor CXCR4 expressions in malignant tissues have been reported, but its role in gastric cancer prognosis remains unknown." (PMID 23936528, 2013). "CXCR4 signaling has been implicated in tumor growth, intravasation, migration, and survival, and optimal use of CXCR4 inhibition may be a part of potential multimodality therapy for gastric cancer treatment." (PMID 23936528, 2013). "Integration of intratumoral CXCR4 density into current clinicopathologic TNM stage system might add some prognostic information for patients with gastric cancer." (PMID 23936528, 2013).
gastric cancer (continued). "In gastric cancer, studies show that CXCR4 promotes metastasis to the lymph nodes." (PMID 24259307, 2013). "As reported, over-expressed CXCR4 also plays an important role in cancer metastasis and is involved in the EMT process, which suggested that CXCR4 might be a downstream gene of RhoE with importance in the metastasis of gastric cancer cells." (PMID 24312338, 2013). "Previous study has been demonstrated CXCR4 antagonists maybe useful for the treatment of peritoneal carcinomatosis of gastric cancer in a mouse model." (PMID 23936528, 2013). "In order to ascertain whether CXCR4 protein is elevated in gastric cancer tissues, we first evaluated CXCR4 expression by immunohistochemical analyses in tumor and paired non-tumoral specimens from 97 patients with gastric cancer." (PMID 23936528, 2013). "In addition, CXCR7 is also a receptor for CXCL12 that binds this chemokine with greater affinity, the clinical and prognostic implications of CXCL12/CXCR4/CXCR7 axis in patients with gastric cancer remain to be elucidated in future." (PMID 23936528, 2013). "To investigate the effect of CXCR4 on the ability of RhoE to function in the metastasis of gastric cancer, we enhanced the expression of CRCR4 in SGC7901-M-siRhoE cells by lentiviral tranduction and down-regulated its expression in SGC7901-NM-RhoE cells by siRNA interference." (PMID 24312338, 2013). "Taken together, our findings indicate that intratumoral CXCR4 expression may be a useful marker to predict the survival of patients with gastric cancer." (PMID 23936528, 2013). "Our data also showed that plumbagin suppressed CXCR4 expression on various tumor cell lines including gastric cancer, lung adenocarcinoma, renal cell carcinoma, oral and hepatocellular carcinoma, thereby indicating that the effect of plumbagin on CXCR4 is not limited to a single tumor cell type." (PMID 21880153, 2011). "Indeed, we found that plumbagin downregulated the expression of CXCR4 mRNA in breast and gastric cancer cells." (PMID 21880153, 2011). "The previous researches led to our conclusion that CXCR4 overexpression in biopsy specimen of primary gastric cancer may serve as a preoperative evaluation of risks for the occurrence of peritoneal carcinomatosis." (PMID 20699000, 2010). "Studies have indicated CXCL12/CXCR4 axis is involved in gastric cancer metastasis." (PMID 20699000, 2010). "When expressing both, CXCL12 in tumour cells and CXCR4 in tumour microvessels, these tumours also were significantly associated with higher T- and UICC-stages, supporting the role of the CXCL12-CXCR4 axis in neoangiogenesis of gastric cancer." (PMID 20386750, 2010). "Therefore it arouses great interests to find a link between H. pylori infection and CXCR4 overexpression in gastric cancer." (PMID 20699000, 2010). "TNF-α is involved in the upregulation of CXCR4 expression in gastric cancer induced by H. pylori." (PMID 20699000, 2010). "Some human gastric carcinoma cells also express CXCR4 mRNA and protein at high levels." (PMID 20699000, 2010). "T2b/T3/T4-stage gastric carcinomas more likely harbour a hypoxic microenvironment than T1/T2a-stage tumours and thereby might induce CXCR4 gene expression and angiogenesis." (PMID 20386750, 2010). "29% of gastric carcinomas showed CXCR4 positive tumour microvessels." (PMID 20386750, 2010). "In line with this theory, a strong CXCR4 expression was associated with noninvasive gastric cancers and not with lymph node metastases." (PMID 16819541, 2006). "Therefore, activation of either of these two receptors results in an increased expression of CXCR2 and CXCR4, which translates into an increase in gastric cancer cell migration and epithelial-to-mesenchymal transition (EMT) induction of these cells, an effect also significant in metastasis." (PMID 37408240, 2023). "Therefore, future studies need to further explore whether CXCR4 mediates gastric cancer occurrence and chemotherapy resistance." (PMID 37679408, 2023).
gastric cancer (continued). "However, a comprehensive analysis of CXCR4 expression concerning the prognosis of patients with gastric cancer remains unknown and needs to be fully established." (PMID 35877436, 2022). "Therefore, we investigated whether KDM6B plays a cancer promoting role in gastric cancer cells that depends on the CXCL12/CXCR4 signaling pathway." (PMID 36564369, 2022). "Based on TCGA data, the high expression of CXCR4 in GC was positively correlated with the advanced stage and grade of gastric cancer and related to poor prognosis." (PMID 34322132, 2021). "At the same time, CXCR4 may be used as a promising prognostic indicator for gastric cancer." (PMID 34759953, 2021). "The results showed that CXCR4 was up-regulated in all N-stages of GC, with the strongest expression in N1 stage gastric cancer." (PMID 34322132, 2021). "Certainly, some other cells can also express CXCR4 in GC, such as gastric cancer cells, myeloid cells, myeloid-derived suppressor cells (MDSCs) and so on." (PMID 30808413, 2019). "Thus, we believe that Cxcr4+ epithelial cells, which include the Mist1+ antral progenitors, contribute to human gastric cancer progression, and that the Cxcr4/Cxcl12 axis may still be a promising therapeutic target against broad spectrum of gastric cancers." (PMID 29340033, 2017). "We revealed the potential anti-tumor effects and underlying mechanisms of regorafenib in gastric cancer cells, and CXCR4 might mediated the anti-tumor effect of gastric cancer cell to regorafenib, and might be a novel biomarker for patients selecting of regorafenib." (PMID 28489887, 2017). "Similarly, it has been cleared that CXCR4 is expressed on the cell surface of gastric cancers." (PMID 24659999, 2014). "In addition, both RhoE and CXCR4 expression were concordant in 83.3% (50/60) of gastric carcinomas specimens, the Spearman R correlation coefficient was 0.80 (P <0.001) and indicated a close correlation between both RhoE and CXCR4 expression in gastric cancers." (PMID 24312338, 2013). "This contrary finding might reflect the different IRS criterion and different genetic background of patients with gastric cancer, and the profound molecular roles of CXCR4 in gastric cancer differentiation remain far from fully understood and merit further investigation." (PMID 23936528, 2013). "However, a comprehensive analysis of CXCR4 expression in relation to survival of patients with gastric cancer remains largely unknown and needs to be further established." (PMID 23936528, 2013). "Interestingly, about one third of the gastric carcinomas showed CXCR4 positive tumour microvessels." (PMID 20386750, 2010). "MSI gastric cancers showed an increased total number of CD8+ T cells, albeit with a lower proportion of CD8+ CXCR4+ T cells, compared to MSS counterparts." (PMID 39552563, 2025). "A study reported that the expression of CXCR4 and CXCR2 is positively correlated in gastric cancer and that a positive feedback loop is formed between P65/CXCR4 and STAT3/CXCR2, which induces EMT and promotes metastasis." (PMID 40722739, 2025). "MSI gastric cancers showed an increased total number of CD8+ T cells, albeit with a lower proportion of effector memory cells expressing CD45RA (EMRA) and CD8+ CXCR4+ T cells, compared to MSS counterparts." (PMID 39552563, 2025). "Taken together, these findings further suggested the critical roles of CXCR4 and NFE2L2 in predicting the prognosis of stage I and stage II gastric cancer patients." (PMID 38221932, 2024). "With a deeper understanding of these mechanisms, the DARPP-32/CXCR4/CXCL-12 complex axis should be considered a type of targeted therapy to inhibit tumor progression and improve outcomes in patients with gastric cancer." (PMID 39767693, 2024). "CXCR4, SPP1, CXCL1, MMP9, and TIMP1 were up-regulated and NFE2L2 was down-regulated in gastric cancer cell lines compared with control." (PMID 38221932, 2024).